LINC01194 (long independently transcribed non-coding RNA 1194)
Synonyms: TAG; CT49
Gene: Long non-coding RNA gene on chromosome 5 (12,574,814 to 12,862,171, forward strand). Ensembl gene ENSG00000248131.
Diseases named in the same sentence as LINC01194 in open-access papers:
LINC01194 is named in the same sentence as 53 diseases in open-access papers, as found by Europe PMC text mining. Sharing a sentence is not in itself a finding about the gene and the disease. The quoted sentences say what the papers report.
colorectal cancer (10 papers, 2017 to 2024). A primary or metastatic malignant neoplasm that affects the colon or rectum. "The index case 27.1 (56 years old, oral cavity tumor) and her sister (27.2, 58 years old, colorectal cancer) shared the same deletion on chromosome 5p15.2, covering an intronic region of the LINC01194 gene." (PMID 36552033, 2022). "Previously, LINC01194 has been suggested to play oncogenic parts in several different cancer types, such as colorectal cancer and laryngeal squamous cell carcinoma." (PMID 33372601, 2020).
tumor (94 papers, 2007 to 2025). "LINC01194 serves as a tumor promotor, and enhances progression of PCa by regulating LINC01194/miR-486-5p/GOLPH3 axis." (PMID 37025585, 2023).
cancer (46 papers, 2007 to 2026). A tumor composed of atypical neoplastic, often pleomorphic cells that invade other tissues. "LncRNA LINC01194 acts as an oncogene in several cancer types." (PMID 33372601, 2020).
LINC01194 also shares sentences with these, for which no sentence is quoted: melanoma (27 papers); ovarian carcinoma (14); breast carcinoma (10); prostate carcinoma (10); multiple myeloma (8); renal cell carcinoma (5); hepatocellular carcinoma (4); lung carcinoma (4); neuroblastoma (4); pancreatic cancer (4); colon cancer (3); glioblastoma (3); non-small cell lung carcinoma (3); bladder cancer (2); gastric cancer (2); prostate tumors (2); acute myeloid leukemia (1); adenocarcinoma (1); B cell lymphoma (1); Bladder urothelial carcinoma (1); brain tumors (1); cervical and (1); cervical cancer (1); chondrosarcoma (1); chronic leukemia (1); chronic lymphocytic leukemia (1); clear cell renal cell carcinomas (1); COVID-19 (1); esophageal squamous cell carcinoma (1); glioma (1).
A further 20 diseases each share a sentence with LINC01194 in 1 paper.